AKT2 (AKT serine/threonine kinase 2)
Diseases named in the same sentence as AKT2 in open-access papers (continued):
Sharing a sentence is not in itself a finding about the gene and the disease.
Insulin resistance (continued). "Irs1 and Irs2, as also Akt2 are essential for the development of steatosis in the presence of insulin resistance." (PMID 27708333, 2016). "Incubation of MIN6 cells with 4 μM Akti-2, which selectively inhibits Akt2, led to an increase in insulin resistance in 50% of the analyzed cells." (PMID 26899548, 2016). "Data from mouse models discordant for obesity and insulin resistance (AKT2 KO, Adiponectin aP2-transgenic), suggested that scWAT TAG Elovl6 ratio was associated with insulin sensitivity, whereas SCD1 ratio was associated with fat mass." (PMID 26679101, 2015). "An autosomal dominant missense mutation, R-H274, which affects the activation segment and catalytic loop of Akt2 has been indicated to result in severe insulin resistance and diabetes." (PMID 26465754, 2015). "Akt -1, -2, -3 are three isoforms of Akt in insulin sensitive tissue, and defective signaling through Akt-2 and -3 mediates insulin resistance in human skeletal muscle." (PMID 24349318, 2013). "It has been reported that Akt2-null mice develop insulin resistance and mild hyperglycemia with hyperinsulinemia as Akt2 is a key protein involved in signal transduction." (PMID 23805905, 2013). "Further, AKT2 gene knockout mice exhibit glucose intolerance and systemic insulin resistance." (PMID 38799166, 2024). "Other studies have found that interrupting AKT2 may lead to severe insulin resistance, diabetes, and fat atrophy." (PMID 38799166, 2024). "However, fructose contributes to hepatic insulin resistance through increased accumulation of hepatic diacylglycerol, activation of protein kinase C, impairment of insulin-mediated Akt2 activation, and blocking of hepatic β-fatty acid oxidation." (PMID 39458565, 2024). "As Akt2 is essential in insulin resistance, we further tested whether the inhibition of Akt2 signaling could suppress insulin‐dependent glucose uptake." (PMID 36625257, 2023). "Indeed, our results indicate that senescent myoblasts showed signs of insulin resistance as they lost the ability to phosphorylate Akt2 in response to insulin." (PMID 36797255, 2023). "Transgenic AKT2-knock-out (KO) mice develop insulin resistance and a T2D-like phenotype." (PMID 33893069, 2021). "Several studies have linked insulin resistance to a dysfunctional Akt2 where its secretion is less than 50% compared with non-insulin resistant conditions." (PMID 33953863, 2021). "However, with adipose tissue insulin resistance, there is a decrease in Akt2 phosphorylation, resulting in sustained lipolysis activation." (PMID 33038072, 2020). "PEPD attenuated insulin-induced AKT2 phosphorylation, resulting in increased insulin resistance." (PMID 32722593, 2020). "Furthermore, in an Akt2 KO-induced model of insulin resistance, trehalose ameliorated insulin resistance-induced kidney and skeletal muscle injury, excessive autophagy, and apoptosis." (PMID 31936109, 2020). "Indeed, high insulin levels have been shown to enhance BCAA uptake in the liver of obese rats and promote further severe liver insulin resistance by the attenuation of Akt2 signaling via mTORC1- and mTORC2-dependent pathways." (PMID 32823827, 2020). "Furthermore, qRT-PCR results indicated that VT influenced the expression of Irs1, Akt2, Mtor genes in the Akt signaling pathway, suggesting that VT enhanced insulin signaling and improved liver insulin resistance." (PMID 31096578, 2019). "Severe hepatic insulin resistance was characterized using the hyperinsulinemic-euglycemic clamp technique and was attributed to increased hepatic diacylglycerol content and protein kinase C-epsilon activation and decreased insulin activation of Akt2." (PMID 28163820, 2017). "This feature might be beneficial in clinical settings, where strong inhibition of Akt2 might lead to insulin resistance." (PMID 28903409, 2017). "Knockout of Akt2 led to insulin resistance and diabetes mellitus." (PMID 28224045, 2017).
Insulin resistance (continued). "Interestingly, when Akt2 was deleted in knockout mice, increased insulin resistance was observed illustrating the important physiological role played by Akt2 in mediating glucose homeostasis." (PMID 26257839, 2015). "While AKT2 deficiency impairs insulin action on liver metabolism, elevated basal AKT activity contributes to insulin resistance in obese mice induced by HFD and elevated basal PI3K signaling is associated with insulin resistance in skeletal muscle and glucose intolerance in men." (PMID 22412882, 2012). "However, a previous study showed that exercise only restored Akt1 expression in rats with HFD-induced insulin resistance, and Akt2 content was unchanged." (PMID 23272147, 2012). "Existing literature proposes that Yerba Maté polyphenols could potentially modulate hepatic insulin signaling by suppressing TNF-α, and may interact with the PI3K-AKT pathway, involving elements like Akt2 and Irs1, possibly contributing to improved peripheral insulin resistance." (PMID 41244043, 2025). "Novel Akt2 interactions may further elucidate insulin signaling and provide insight into abnormal Akt2 protein interaction that contributes to the development of insulin resistance and/or type II diabetes." (PMID 26465754, 2015). "Indeed, hepatic ablation of Akt1 and Akt2 contributes to glucose tolerance and insulin resistance." (PMID 25888638, 2015). "Therefore, our results linking PI3K-C2γ with Akt2 and metabolic control in the liver provide a molecular mechanism for this association and suggest this PI3K-C2γ as a key element protecting from age-associated and diet-related insulin resistance." (PMID 26100075, 2015). "However, despite this relatively improved benefit of combining MK2206 and gefitinib in EGFR M+ cells, preclinical data using mouse models has shown that combined inhibition of both AKT1 and AKT2 can result in insulin resistance as well as hyperglycaemia and hyperinsulinaemia." (PMID 24946858, 2014). "R. roxburghii has been demonstrated to ameliorate insulin resistance in obese rats through the induction of antioxidant stress and augmentation of the expressions of PI3K, Akt2, and GLUT4 proteins and genes." (PMID 38611854, 2024). "Reduced mRNA expression of AKT2, SREBF1 and GLUT4 in the subcutaneous adipose tissue, as well as the downregulation of SREBF1-regulated lipogenic genes, indicated insulin resistance occurred in early lactation cows." (PMID 39881718, 2024). "For example, the L. casei strain, whose abundance is favored by curcumin, improves insulin resistance precisely through the PI3K, AMPK2, Akt2, and hepatic glycogen synthesis pathways." (PMID 39062953, 2024). "In other studies, acute induction of muscle insulin resistance increased DAG content, PKCθ activation, and increased phosphorylation of IRS1 serine 1,101, concurrent with inhibition of IRS1 and Akt2 phosphorylation." (PMID 33038072, 2020). "Hepatic insulin resistance is an important pathophysiological feature of obesity, and PI3K/Akt2 are the main components of the insulin signalling pathway." (PMID 31270932, 2019). "We confirmed that Ln4 administration induced the up-regulation of hepatic mRNA levels, including IRS2, Akt2, and AMPK, and these results correspond to the data of improving systemic insulin resistance in Ln4-treated mice." (PMID 29783731, 2018). "ILG appeared to improve insulin resistance by increasing IRS2 and AKT2 mRNA levels in the skeletal muscle." (PMID 30360437, 2018). "The insulin resistance subphenotype of SHORT syndrome patients, who have a functional defect lying between INSR and AKT2 in the insulin signaling pathway, closely resembles that seen in INSR dysfunction." (PMID 27766312, 2016). "Despite decreased AKT2 mRNA at week 2 (−28.6%, P = 0.002) and increased PTPN1 mRNA at week 24 (+50.3%, P = 0.016) suggesting insulin resistance, clinical insulin sensitivity [by homeostasis model assessment (HOMA-IR)] was unchanged." (PMID 27516476, 2016).
Insulin resistance (continued). "In order to understand the mechanism by which ApoA5 ASO-treated mice were protected from lipid-induced liver and muscle insulin resistance, we assessed DAG and ceramide content, nPKC translocation, and insulin-stimulated AKT2 phosphorylation in these tissues." (PMID 25548259, 2015). "Significantly improved insulin resistance by restoring hepatic FOXO1 nuclear translocation and upregulating gene expression of Akt2, Irs1, Irs2, Pi3kca, Pi3kcg and Pdk1." (PMID 25621503, 2015). "ApoC3Tg mice also manifested severe hepatic insulin resistance assessed by a hyperinsulinemic-euglycemic clamp, which could mostly be attributed to increased hepatic diacylglycerol content, protein kinase C-ε activation, and decreased insulin-stimulated Akt2 activity." (PMID 21793029, 2011). "L. casei improves insulin resistance using phosphatidylinositol-3-kinase (PI3K) pathway, the 5′-AMP-Actived Protein Kinase Catalytic Submit-2 (AMPK2), Protein Kinase B (Akt2 o RAC-beta serine/threonine-protein chinase), and controls the synthesis of hepatic glycogen." (PMID 39062953, 2024). "In conclusion, exenatide may improve hepatic insulin resistance (IR) by inhibiting adipokines and regulating the expression of key proteins in the IRS2/PI3K/Akt2 pathway." (PMID 36246878, 2022). "The AKT2 is the most abundant AKT isoform in human insulin-sensitive cells and plays a pivotal role in insulin’s metabolic response, especially in type 2 diabetes mellitus and insulin resistance." (PMID 35906673, 2022). "We implemented a combined bioinformatics analysis to retrieve a set of ceRNA networks (LncRNA-RP11-773H22.4, miR-1, miRNA-3163, which is related to insulin resistance and their targeting signaling pathway genes RET, IGF1R, GLUT4, AKT2 and mTOR mRNAs) from public databases." (PMID 34360895, 2021). "In this regard, mice lacking both hepatic isoforms (Akt1:Akt2) show marked glucose intolerance and insulin resistance." (PMID 29709004, 2018). "Akt2 is a key to insulin function, as mice lacking Akt2 have insulin resistance and a diabetes mellitus-like syndrome occurred." (PMID 30116147, 2018). "Decreased mRNA and protein levels of insulin receptor β (qPCR: Insr; protein: IRβ) and increased Akt2 mRNA and total AKT protein levels in the Yoyo group, compared to Chow and/or HFD > Chow mice are further highlighting an impaired glucose metabolism and insulin resistance after weight cycling." (PMID 39754229, 2025). "However, the gene expression of AKT2, SREBF1, and GLUT4, and lipogenic genes regulated by insulin was significantly lower in the INS_K group, indicating that some cows have more severe insulin resistance that cannot be relieved by exogenous insulin supplementation." (PMID 39881718, 2024). "Similarly, mice lacking Akt2 are prone to hyperglycemia and insulin resistance; the absence of Akt2 in macrophages promotes the anti-inflammatory M2 phenotype and reduces AS." (PMID 34956379, 2021). "However, simultaneously knockout of AKT2 and AKT3 causes reduction of body weight and insulin resistance but is not accompanied by lethality." (PMID 31752925, 2019). "Thus, PIK3R1 C-terminal mutations impair insulin signaling only in some cellular contexts and produce a subphenotype of insulin resistance resembling INSR dysfunction but unlike AKT2 dysfunction, implicating PI3K in the pathogenesis of key components of the metabolic syndrome." (PMID 27766312, 2016).
ovarian carcinoma (81 papers, 2005 to 2026). A malignant neoplasm originating from the surface ovarian epithelium. "We focused on AKT1 and AKT2 isoforms, which are expressed in most tissues and have been implicated in ovarian cancer pathogenesis in multiple studies." (PMID 33488949, 2020). "The overexpression of Akt2 has also been linked to an increased β integrin expression, which in turn led to increased invasion and metastasis of human breast and ovarian cancer cells." (PMID 30288178, 2018). "RNA-IP microarray analysis suggested that LIN28B binds to mRNAs that are associated with the DNA damage pathway, such as AKT2, in ovarian cancer cells." (PMID 30174831, 2018). "In fact, the chemoresistance associated with AKT2 in ovarian cancer is related to the inability of cisplatin to activate JNK and p-38 to induce apoptosis." (PMID 28008141, 2017). "AKT2 amplification was particularly associated with high-grade aggressive ovarian cancers and appeared to occur as part of the frequent amplification of the 19q13.1–q13.2 chromosomal region." (PMID 26818920, 2016). "The AKT2 oncogene contained in this region of chromosome 19, has been shown to be associated with the progression of ovarian cancer." (PMID 16042759, 2005). "Additionally, recent studies have identified mutations in the AKT-2 gene as a potential contributor to ovarian cancer development and progression." (PMID 37239452, 2023). "Notably, amplification of the 19q13.2 region in the ovarian cancer c6 subtype harboring the AKT2 gene is associated with poor survival which was consistent with previous findings that AKT2 amplification is associated with ovarian cancer aggressiveness." (PMID 33272320, 2020). "The AKT2 gene is overexpressed in about 12% of ovarian cancer specimens, which indicates that it may be linked to the etiology of the disease." (PMID 21967738, 2011). "Increasing studies demonstrate the important role of AKT2 in cancers as an oncogene which is closely associated to tumor aggressiveness by enhancing the survival, migration and invasion of cancer cells primarily, and overexpress in many human tumors including BC and ovarian cancer." (PMID 27175587, 2016). "However, AKT2 has also been linked to the maintenance of a Cisplatin resistant phenotype of ovarian carcinomas: it was shown that AKT2 inhibition re-sensitized Cisplatin resistant ovarian cancer cells." (PMID 21967738, 2011). "A large-scale multicenter study found that the overexpression of AKT2 was present in 12% of ovarian cancers (16/132) and 3% of breast cancers (3/106)." (PMID 40746599, 2025). "In a mouse model, knockdown of Akt1 significantly inhibited ovarian cancer cell proliferation and in vivo tumor progression, whereas disruption of Akt2 increased tumor growth." (PMID 39614261, 2024). "Experimental work showed that overexpression of AKT2 in ovarian carcinoma cells correlated with increased invasion and metastasis." (PMID 39614261, 2024). "AKT2 expression was increased in primary ovarian carcinomas in comparison with normal ovaries by immunohistochemistry." (PMID 38238671, 2024). "Based on the results of the experiments and bioinformatics analyses, it is inferred that the target gene CENP-O exerts its effects in ovarian cancer cell disease by regulating genes such as AKT2, JAK2, and MMP9 in SK-OV-3 cells." (PMID 38890751, 2024). "Akt2 can promote migration and invasion by upregulation of β1-integrin in breast and ovarian cancer cells or by increasing the actin-bundling protein palladin." (PMID 38291468, 2024). "AKT2 (RAC-beta serine/threonine-protein kinase) is overexpressed in ovarian cancer and pancreatic carcinoma." (PMID 35163434, 2022).
ovarian carcinoma (continued). "Akt2 gene copy number gain was found in ovarian cancer, pancreatic carcinoma, liver cancer, colorectal carcinoma, gastric carcinoma and breast neoplasm." (PMID 36539659, 2022). "The same is observed in ovarian cancer cell lines, again involving AKT2 knockout and the same two inhibitors (at FDR = 9% and 12%, respectively)." (PMID 35614096, 2022). "The same study showed a more prominent increase of apoptosis (5.5-fold) and decrease of proliferation (51%) following knockdown of AKT2 in the OVCAR8 cell line, known to have a copy-gain of AKT2, compared to the other ovarian cancer lines tested." (PMID 35582310, 2021). "Akt also plays an essential role as an anti-apoptotic mediator, where siRNA knockout of the Akt1 and Akt2 isoforms results in increased apoptosis and reduced proliferation in ovarian cancer." (PMID 34316328, 2021). "We demonstrated that the depletion of ovarian cancer cell lines from pro-survival AKT1 isoform results in more increased cell death than the depletion of AKT2 isoform." (PMID 33488949, 2020). "Transfection of human AKT2 cDNA into human breast and ovarian cancer cells increased the invasion and metastasis ability of tumor cells by up-regulating integrin β12." (PMID 32211805, 2020). "LIN28B inhibits the apoptosis of ovarian cancer cells and promotes cancer progression by binding to AKT2 mRNA and increasing the expression of the protein." (PMID 33193718, 2020). "AKT2 levels were higher in ovarian cancer lines than in the other two cancer types, consistent with previous studies showing that AKT2 is frequently amplified in ovarian cancer." (PMID 30012111, 2018). "With this approach, the distinct roles of AKT1 as a growth inducer and AKT2 as a growth and invasion repressor were well defined in ovarian cancer cells, both within the tumor and the microenvironment." (PMID 28287129, 2017). "Concerning ovarian cancer, it has been demonstrated that AKT2 expression increase resistance to cisplatin." (PMID 28008141, 2017). "In a study on ovarian cancer cells, AKT2 inhibits GAPDH nuclear translocation and suppresses GAPDH-induced apoptosis." (PMID 25859407, 2015). "Intriguingly, the ovarian cancer tissues that exhibited lower miR-29b expression also showed higher levels of AKT2 and AKT3 compared to their counterparts that exhibited higher miR-29b expression." (PMID 26512921, 2015). "We then assessed the changes in the expression of AKT2, AKT3, and the four glycolytic enzymes caused by silencing endogenous miR-29b expression in the two ovarian cancer cell lines with constitutively high endogenous miR-29b expressions (A2780 and 3AO)." (PMID 26512921, 2015). "Important glucose metabolism events, including glucose consumption and lactate production, were examined in ovarian cancer cells over-expressing AKT2/3." (PMID 26512921, 2015). "Briefly, ovarian cancer cells were transfected with miR-29b or control mimics in addition to a luciferase construct containing either the wild-type AKT2/AKT3 3′UTR or a mutant AKT2/AKT3 3′UTR." (PMID 26512921, 2015). "Here, we report that miR-29b negatively regulates AKT2/AKT3 expression, causing HK2/PKM2 downregulation and leading to a decreased Warburg effect and slowed ovarian cancer progression." (PMID 26512921, 2015). "They provided evidence that this hypoxia-activated, Akt2-dependent pathway is present in ovarian cancer through examining a panel of ovarian cancer cell lines in vitro as well as real-time PCR analysis of 31 human ovarian cancer samples." (PMID 24744103, 2014). "Supporting an important role for Akt2 in cell migration, Akt2 overexpression upregulates β1 integrin, which increases invasion and metastasis of human breast and ovarian cancer cells." (PMID 25240046, 2014). "AKT1 activity is frequently elevated in breast and prostate cancers while AKT2 has been shown to be upregulated in pancreatic and ovarian carcinomas." (PMID 21869924, 2011).